GDF15 (growth differentiation factor 15)
Diseases named in the same sentence as GDF15 in open-access papers (continued):
Sharing a sentence is not in itself a finding about the gene and the disease.
cancer (continued). "This makes GDF15 a prognostic factor for diseases like cardiac disease, lung disease, cancer, neurodegenerative disease, and metabolic syndrome." (PMID 38255875, 2024). "This study aims to evaluate the relationship between serum GDF-15 and IL-6 levels and their impact on immunotherapy response in cancer patients." (PMID 39766045, 2024). "Further support for both TXNIP and ARRDC4’s role in regulating GDF15 after the induction of ROS comes from a pan cancer meta-analysis assessing the impact of metformin (which has been reported to inhibit ROS) on gene expression." (PMID 39103698, 2024). "Innovative therapeutic approaches are being explored, including the use of pharmaceuticals initially developed for obesity and cancer that target GDF15." (PMID 39311313, 2024). "In cancer cachectic patients, GDF-15 blocking antibody Ponsegromab increased weight and improved quality of life." (PMID 38686386, 2024). "NGM Biopharmaceuticals has successfully developed NGM120, a novel antagonistic antibody that binds to GFRAL and inhibits the signaling of GDF15, demonstrating promising potential in cancer treatment." (PMID 39172988, 2024). "In cancer patients, circulating levels of GDF15 are significantly elevated compared to those in healthy individuals, and this elevation is associated with weight loss, poor prognosis, and decreased survival rates." (PMID 39172988, 2024). "A useful parallel, as regards understanding the GDF15 system and its evolution, comes from the only other context where this hormone is expressed at extremely high levels: in cancer." (PMID 38711789, 2024). "Experimental evidence has shown that GDF15 expression in cancer cells can be upregulated by drugs, and upregulation of GDF15 presents in tumor-suppressive circumstances." (PMID 38360722, 2024). "This is consistent with existing literature on GDF15’s role in exercise and cancer, demonstrating a U-shaped dose-response to stress." (PMID 39737171, 2024). "In summary, the performance of the neutralizing antibody KY-NAb-GDF15 is remarkable, showing great potential in the treatment of cancer cachexia and in GDF15-related detection fields." (PMID 39172988, 2024). "While delivery before GDF15 increases would be a feasible approach for cancer cachexia, it is less feasible for HG treatment." (PMID 39311313, 2024). "It seems that GDF15 signaling stimulates apoptosis in acute cell damage, e.g., after excessive drug treatments of cancer cells or overwhelming ER stress in mouse β-cells." (PMID 39643709, 2024). "Studies have shown that GDF15 inhibits tumor growth in the early stage of cancer but promotes tumor cell proliferation in the late stage." (PMID 38213743, 2024). "Several pathological conditions show elevated plasma GDF-15 levels, including metabolic, cardiovascular, and hematological diseases and cancer, reaching concentrations up to one hundred times the physiological value." (PMID 39000420, 2024). "Ponsegromab (PF‐06946860) is a potent and highly selective humanized monoclonal antibody directed against GDF‐15 that is currently being investigated in patients with cancer, cachexia and elevated circulating concentrations of GDF‐15." (PMID 38500292, 2024). "The successful development of KY-NAb-GDF15 plays a pivotal role in advancing therapies for cancer cachexia and facilitating the progress of corresponding antibody-based treatments." (PMID 39172988, 2024). "Vigorous endurance exercise, which induces transient mitochondrial stress, spikes plasma GDF15 comparable to patients with MD, infection, and cancer." (PMID 39737171, 2024). "It is known that GDF15 signaling can suppress the surveillance of cancer cells and thus enhance their evasion from the immune clearance by cytotoxic NK and CD8+ T cells." (PMID 39643709, 2024). "Several studies have explored its role in predicting mortality in patients with cardiovascular disease, cancer, and chronic illnesses, highlighting the importance of GDF15 in prognostic models." (PMID 39625596, 2024).
cancer (continued). "Plasma levels of GDF15 also increase in most types of cancer, chronic inflammatory diseases, cardiovascular and renal diseases, severe infections, and can predict all-cause mortality." (PMID 38892145, 2024). "Given these merits, several pharmaceutical companies have begun to study GDF15 monoclonal antibodies for the treatment of malignant tumors and advanced cancer‐induced cachexia." (PMID 38704691, 2024). "In the group demonstrating immunoresistance, heightened TGF‐β production activity was detected in MUC1+ cancer cells, and they were skewed to interplay with C1Q+ macrophages through the GDF15‐TGF‐βR2 axis." (PMID 39422697, 2024). "As such, high GDF15 expression in cancers apparently represents an example of ‘co-option’ by cancers of mechanisms that evolved in the context of invasive, hemochorial placentation, a pattern seen for many other molecules and pathways as well." (PMID 38711789, 2024). "In the early stages of cancer, the presence of GDF-15 in the tumor microenvironment would reduce the M1 phenotype and thus the immune surveillance, favoring tumor growth." (PMID 39000420, 2024). "This accompanying diagnostic method can be used for the detection of the disease biomarker GDF15 in human physical examinations, serving as a preliminary screening for cancer or inflammation." (PMID 39172988, 2024). "Currently, several clinical trials are ongoing to evaluate the therapeutic potential of using GDF15 as a target for cancer cachexia." (PMID 39697630, 2024). "At rest, GDF15 is produced at low levels by most epithelial tissues, however in cancers it is frequently overexpressed, particularly in hepatocellular carcinoma, prostate cancer and colorectal cancer." (PMID 39103698, 2024). "We first measured the levels of IL-6 and GDF-15 in the blood at different timepoints of cancer progression in this model." (PMID 38824130, 2024). "In contrast, GDF-15 is a member of the transforming growth factor-β cytokine superfamily and plays various roles in cardiovascular disease, inflammation, cancer, and kidney disease." (PMID 38515869, 2024). "The immunosuppressive properties of GDF15 have been studied most frequently in cancers, infections, and transplantation as well as somewhat surprisingly in pregnancy." (PMID 39643709, 2024). "So far, these treatments have been well-tolerated by cancer patients and have resulted in a reduction in the circulating levels of GDF15." (PMID 39697630, 2024). "The exact effects and mechanisms explaining GDF-15 behavior in cancer are still controversial and often paradoxical." (PMID 39000420, 2024). "By inhibiting GDF‐15‐mediated signalling, ponsegromab has the potential to ameliorate the key pathologies of cancer cachexia to improve patient symptoms, functionality and quality of life." (PMID 38500292, 2024). "The primary objective of this phase 2 study is to assess the effect of ponsegromab on body weight in patients with cancer, cachexia and elevated GDF‐15 concentrations." (PMID 38500292, 2024). "Collectively, these data support the potential therapeutic relevance of targeting GDF‐15 in the management of cancer cachexia." (PMID 38500292, 2024). "Some studies described GDF-15 in the context of cardiotoxicity in cancer treatment with doxorubicin, taxanes or trastuzumab or due to radiation." (PMID 38398274, 2024). "In studies on various cancers, the plasma/serum threshold of GDF15 was reported to be 1000–1500 pg/mL." (PMID 36472770, 2023). "Although GDF15 is a well-known poor prognostic factor in a wide variety of cancers, the potential role of circulating GDF15 as a candidate predictor of chemoresistance and clinical outcomes has not yet been investigated comprehensively." (PMID 36472770, 2023). "Growth differentiation factor 15 (GDF15), an inflammatory marker and mediator of adult cancer cachexia, remains largely unexplored in children." (PMID 38146512, 2023).
cancer (continued). "Taken together, these results indicated that ELFN1-AS1 in CRC cells promoted the immune escape of the cancer cells from NK cells by facilitating GDF15 synthesis and secretion." (PMID 37147528, 2023). "In NCI-60 cancer cell lines, we observed different effects on GDF15 expression for the two FLT3 inhibitors sorafenib and sunitinib." (PMID 37495707, 2023). "Specifically, GDF‐15, one of the key players in skeletal and cardiac muscle wasting, is a promising biomarker for disease outcome and potential target for treating cancer‐induced cardiac cachexia." (PMID 37654192, 2023). "In animal models, both cancer and chemotherapy increase circulating GDF15 levels and correlate with decreased food intake and weight loss." (PMID 38146512, 2023). "Very few bibliographic data have been published on the expression and role of GDF15 in cancer stem cells." (PMID 38201456, 2023). "Whilst a personalized selection of chemotherapeutic agents has the potential to mitigate chemotherapy-driven GDF15 overexpression in cancer cells, it leaves basal overexpression of GDF15 unaffected." (PMID 37495707, 2023). "Clinical significance of GDF15 in ccRCC as well as other types of human cancers was analyzed using the TCGA PANCAN dataset." (PMID 38082448, 2023). "We showed that this basal GDF15 expression gets significantly reduced upon BET inhibition using BI 894999 in a subset of tested cancer cell lines, in which concomitant upregulation of GDF11 was observed." (PMID 37495707, 2023). "Many recent preclinical and clinical studies have identified GDF‐15 as a stress‐hormone released during cancer." (PMID 37654192, 2023). "GDF15 is overexpressed in many cancers (colorectal, gastric, pancreatic, hepatic, ovarian) and is often associated with tumor aggressiveness." (PMID 38201456, 2023). "Factors from the TGF‐β family, such as activin A, myostatin, or GDF15, have also been shown to induce cancer‐mediated cardiac cachexia in tumor models." (PMID 37654192, 2023). "We found that NCI-60 cancer cell lines can be classified in clusters according to the extent of GDF15 induction by different drugs." (PMID 37495707, 2023). "Median GDF15 was higher in the cancer group (N=29) at baseline (median = 614.6 pg/mL, IQR = 420.4-774.2 pg/mL) compared to the control group (N=26; median = 320.5 pg/mL, IQR = 276.6-384.1 pg/mL; p<0.001)." (PMID 38146512, 2023). "Higher GDF15 levels have been observed in older persons, persons with heart disease, and in persons with specific cancers." (PMID 37803875, 2023). "GDF15 expression is elevated and is considered a marker of many pathological states, including inflammation, oxidative stress, and cancer." (PMID 38111379, 2023). "Various types of cancer cells have been reported to heavily secret GDF15 or other factors that induce GDF15 expression in host cells." (PMID 37495707, 2023). "GDF-15 thus represents a predictive biomarker for failure of immune checkpoint blockade, and a new synergistic target for cancer immunotherapy." (PMID 37474523, 2023). "In summary, we found higher GDF15 levels in children with cancer, with persistent elevation at the 3-month follow-up time point compared to the non-cancer controls." (PMID 38146512, 2023). "In contrast to the cardiac-specific nature of cTnT, GDF-15 is a circulating protein that plays a role in both cancers and cardiovascular diseases." (PMID 36844723, 2023). "RNA‐sequencing data extracted from large databases such as The Cancer Genome Atlas demonstrated elevated GDF15 levels in over one dozen different cancer types." (PMID 36642986, 2023). "Here authors show that GDF15, a cytokine that is produced by cancer cells, prevents T cells from extravasation into the tumour microenvironment." (PMID 37474523, 2023).
cancer (continued). "This research is foundational for future studies to examine diagnosis- and treatment-specific patterns of GDF15 in children with cancer in order to determine treatments for childhood cancer cachexia." (PMID 38146512, 2023). "To summarize, our results revealed that BET inhibition reduces basal GDF15 expression in a subset of cancer cell lines that share similar biochemical and metabolic properties." (PMID 37495707, 2023). "Our pilot study compares GDF15 in children with newly diagnosed cancer to age- and sex-matched controls and correlates levels with anthropometric measurements and quality of life (QOL)." (PMID 38146512, 2023). "Due to the heterogeneity of dysregulations in cancer, it can be assumed that every cancer cell line comes with a distinct setting of GDF15-inducing pathway activities." (PMID 37495707, 2023). "We screened various cardiotoxic drugs and BET inhibitors for their effects on GDF15 regulation in human cardiomyocytes and cancer cell lines and analyzed in-house and public gene signature databases." (PMID 37495707, 2023). "GDF15 is a widely overexpressed protein in human cancers and has been extensively investigated as a regulator of many biological processes." (PMID 36769245, 2023). "There has been increasing interest specifically in the role of GDF15 as a biomarker and treatment target in cancer cachexia and other conditions leading to cachexia." (PMID 36642986, 2023). "In large-scale screenings, GDF15 is the most prominently overexpressed soluble factor across a large range of cancer types, including NSCLC." (PMID 36472770, 2023). "Proteins including CXCL14, GDF15, HAVCR1, and CDCP1 were identified as predominant contributors to the risk of cancer." (PMID 38016990, 2023). "To assess anti-GDF-15 treatment against human cancer in vivo, we reconstituted NOD/SCID/γc-/-/FcγR-/- mice with human umbilical cord-derived CD34+ human hematopoietic stem cells." (PMID 37474523, 2023). "Our data also demonstrate a normal distribution of GDF15 in the control population, while the children with cancer showed significant skew toward higher GDF15 levels, but additional study to better characterize GDF15 in healthy children is needed." (PMID 38146512, 2023). "Research has demonstrated that GDF15 plays an important role in regulating the properties of a variety of cancer cells and has a considerable clinical significance for patients with cancer." (PMID 38082448, 2023). "Although elevated circulating GDF15 levels in patients with cancer have been frequently reported, the conflicting effect of this cytokine in predicting disease progression or response to chemotherapeutic agents in cancer has not been fully elucidated." (PMID 36472770, 2023). "Baseline GDF15 was higher in the cancer cohort compared to the control cohort (median=614.6pg/mL and 320.5pg/mL, respectively; p<0.001)." (PMID 38146512, 2023). "Now that we have documented increased GDF15 in children with cancer, future study of specific patterns in individual diagnoses and more longitudinal assessment appear to be warranted." (PMID 38146512, 2023). "Its neutralizing function was first confirmed by its ability to prevent GDF-15-induced cancer cachexia in nude mice xenograft models." (PMID 37474523, 2023). "Blockade of a GDF15/GFRAL/RET interaction with the monoclonal antibody 3P10 resulted in a reversal of cancer cachexia in mouse models." (PMID 35743911, 2022). "Only mature GDF15 levels in the blood can be easily identified, and they are very low in healthy people; nevertheless, they are significantly raised in cancer, cardiovascular disease, liver and kidney disease, and tissue damage." (PMID 35806043, 2022). "The effects of GDF15 in cancer cell metastasis function are divergent either in a highly tissue-specific manner or a cell-specific manner." (PMID 35884930, 2022).
cancer (continued). "These novel data suggest GDF-15 as a potential prognostic biomarker to estimate the severity of cancer in prostate biopsies and to differentiate PCa from BPH." (PMID 36230513, 2022). "In the present study, to study the roles of GDF-15 in cancer cachexia, the levels of GDF-15 in C26 cells and C26 exosomes were detected and compared with that of MC38 cells." (PMID 35379793, 2022). "Using RNA sequence analysis (RNA-seq), we identified changes in gene expression levels in lidocaine-treated cancer cell lines and GDF-15 was upregulated in a lidocaine concentration-dependent manner." (PMID 36008442, 2022). "The expression of GDF15 was related to the tumor types, histologic subtypes, nodal metastasis status, and individual cancer stages." (PMID 36142823, 2022). "Moreover, it has been shown that PCa cells induced cancer-associated fibroblasts and osteocytes to produce GDF-15, resulting in activation of cell proliferation, migration, and metastatic invasion; this may explain why the most frequent metastatic site for PCa cells is bone." (PMID 36230513, 2022). "In the GDFATHER trial (NCT04725474), the possible anti-cachexia effects of a monoclonal anti-GDF-15 antibody in monotherapy or in combination with a checkpoint inhibitor is being evaluated in patients with advanced cancers." (PMID 36361969, 2022). "Upon exposition to 5-FU, cancer cells HCT-15 released EVs enriched in growth/differentiation factor 15 (GDF15), which binds the TGF-βIII receptor." (PMID 35814444, 2022). "Recently, circulating growth differentiation factor 15 (GDF15) was found to be elevated in cachectic cancer patients." (PMID 35646636, 2022). "Consistently, the elevated GDF15 expression was also positively correlated with the patient’s nodal metastasis and individual cancer stages." (PMID 36142823, 2022). "GDF-15 is also an active area of investigation within cancer research, as it has dually-opposing effects including both anti-tumorigenic and pro-metastatic activities depending on cell type studied." (PMID 35821815, 2022). "There is recent evidence that growth differentiation factor-15 (GDF-15) is elevated in cancer patients." (PMID 36230513, 2022). "Growth differentiation factor 15 (GDF15) has been reported to be involved in various physiologic or pathologic pathways including cancer." (PMID 35589688, 2022). "We identified that growth differentiation factor-15 (GDF-15) was commonly upregulated in lidocaine-treated cancer cell lines." (PMID 36008442, 2022). "GDF-15 is actively involved in cancer progression and invasion and impacts the tumor immune environment via mitogen-activated kinase activities." (PMID 36361969, 2022). "Growth differentiation factor-15 (GDF15) is a secretory dimeric protein with widely different functions in tissue-specific and cell-specific presentations in various cancers." (PMID 34662721, 2022). "Nevertheless, the expression of GFRAL and GDF15/GFRAL downstream signaling in cancers are yet to be discovered." (PMID 35884930, 2022). "GDF15 expression is usually significantly elevated in response to histopathological damage, such as ischemic diseases, cancer, and cardiovascular disease, making it a potential disease biomarker." (PMID 35845807, 2022). "Overall, GDF15 plays an important pathophysiological role in cancer, cardiovascular disease, COPD, etc." (PMID 35845807, 2022). "Recent studies have confirmed HSP70 and HSP90, GDF15 and Prolyl 4‐hydroxylase to be responsible for muscle wasting of cancer cachexia in mice." (PMID 36105371, 2022). "Elevated serum levels of GDF-15 have been found in several types of cancer, also confirmed by biopsy analysis of various tumor tissues." (PMID 35872912, 2022). "In this study, we demonstrated that lidocaine induces growth suppression of cancer cell lines through increasing of GDF-15 expression." (PMID 36008442, 2022).